TGFBI (transforming growth factor beta induced)
Diseases named in the same sentence as TGFBI in open-access papers (continued):
Sharing a sentence is not in itself a finding about the gene and the disease.
insomnia (1 paper, 2024). A sleep disorder characterized by difficulty in falling asleep and/or remaining asleep. "The results indicated that TGFBI was consistently identified as a pathogenic factor for insomnia in both the UK Biobank and GWAS-Catalog cohorts." (PMID 38725646, 2024). "Although the underlying mechanism between TGFBI and insomnia remains unknown, we tried to identify potential associations through the discovery of PPI networks." (PMID 38725646, 2024). "Mendelian randomization analysis indicated that elevated levels of TGFBI (OR = 1.01; 95% CI, 1.01–1.02) and PAM ((OR = 1.01; 95% CI, 1.01–1.02) in plasma are associated with an increased risk of insomnia, with external validation supporting these findings." (PMID 38725646, 2024). "Initially, MR analysis to preliminarily identify the protein targets TGFBI and PAM as potential pathogenic factors contributing to insomnia." (PMID 38725646, 2024). "Specifically, elevated levels of TGFBI (OR = 1.01; 95% CI, 1.01–1.02; p = 3.26E-05) and PAM (OR = 1.01; 95% CI, 1.01–1.02; p = 6.32E-07) were found to increase the risk of insomnia." (PMID 38725646, 2024). "The relationship between TGFBI and insomnia was first reported through a genome-wide association analysis of sleep disorder characteristics, which identified TGFBI as a locus for female insomnia symptoms." (PMID 38725646, 2024). "To gain insights into the potential mechanisms underlying the association of TGFBI and PAM with insomnia, we endeavored to construct a PPI network to facilitate our comprehension of the underlying pathways involved." (PMID 38725646, 2024). "Overall, our findings suggested that elevated plasma levels of TGFBI and PAM are connected with an increased risk of insomnia and might be promising therapeutic targets, particularly PAM." (PMID 38725646, 2024). "Our integrative analyses indicate that there is a causal connection between genetically determined levels of circulating TGFBI and PAM and the risk of insomnia, which may serve as appealing drug targets for treating insomnia, especially PAM." (PMID 38725646, 2024). "Based on these results, we hypothesize that TGFBI may contribute to insomnia in conjunction with the regulation of APP and miRNAs, among other factors." (PMID 38725646, 2024). "Because of this, we searched for insomnia-related targets in the GeneCards database and established another PPI network of TGFBI, PAM, and the top 335 targets with correlation scores greater than 1.5, and found some interaction relationships." (PMID 38725646, 2024). "In order to explore the interaction between TGFBI and PAM with marketed drug targets, we screened 137 drug targets for treating insomnia from the DrugBank and the Open Targets databases and attempted to construct a PPT network to study their interaction relationships." (PMID 38725646, 2024). "Lastly, despite our efforts, we did not identify any drug targets associated with TGFBI and PAM in the current treatment of insomnia." (PMID 38725646, 2024). "Further researches are needed to detect the potential mechanisms of TGFBI and PAM in insomnia." (PMID 38725646, 2024). "Thus, we speculate that TGFBI, as a TGF-β-induced protein, may also contribute to insomnia through these pathways." (PMID 38725646, 2024).
intrahepatic cholangiocarcinoma (1 paper, 2022). A carcinoma that arises from the intrahepatic bile duct epithelium in any site of the intrahepatic biliary tree. "TGFBI was previously shown to be overexpressed in intrahepatic cholangiocarcinoma and associated with areas with high EMT changes." (PMID 34548635, 2022).
liver cirrhosis (1 paper, 2022). "When compared to healthy controls, only 7 DEGs, including 6 up-DEGs (TYMP, TYROBP, TGFBI, LILRA2, GNLY, and GZMB) and 1 down-DEG (CD14) were common to CHB, liver cirrhosis, and HCC." (PMID 35265561, 2022).
lupus nephritis (1 paper, 2023). Glomerulonephritis in the context of systemic lupus erythematosus. "It is worth noting that TGFBI plays an important role in the diagnosis and pathogenesis of lupus nephritis and holds promise as a therapeutic target." (PMID 37841281, 2023).
mastitis (1 paper, 2021). Inflammation of breast tissue during lactation or postpartum due to an obstructed duct or infection. "The transforming growth factor beta induced (TGFBI) and IL-10 cytokines are upregulated during E. coli mastitis, as anti-inflammatory cytokines, and persist for the period of the inflammatory response." (PMID 34637035, 2021).
meningioma (1 paper, 2022). A generally slow growing tumor attached to the dura mater. "We noticed that genes such as TGFBI, SNAI1, MMP2, TGFB1, TGFB2, IGFBP7, and LTBP2 were upregulated by the treatment of M2-MDEs in meningioma cells and may contribute to tumor invasion and proliferation behavior." (PMID 35637794, 2022).
muscle disorders (1 paper, 2025). "By promoting myogenic differentiation and limiting inflammation and fibrosis, TGFBI emerges as a promising therapeutic target for muscle disorders characterized by impaired regeneration, chronic inflammation, or fibrosis." (PMID 41009607, 2025).
nodular goiter (1 paper, 2021). Goiter characterized by discrete tissue mass(es) that may or may not produce thyroid hormones. "CHST6, FBP2, PPFIA4, and TGFBI proteins were all upregulated in THCA tissues compared with nodular goiter tissues." (PMID 33981593, 2021).
oral cancer (1 paper, 2021). "Indeed, TGFBI is one of the p-EMT hallmark proteins present in oral cancer tissues and is implicated in DDR1-mediated angiolymphatic invasions in the NCKU-OrCA-40TN cohort." (PMID 34869001, 2021). "Our results not only disclose novel targets for oral cancer control, but also provide feasible applications, e.g, a single immunohistochemical assay of TGFBI from treatment naïve or recurred tumor biopsies, to assist clinical decision-making." (PMID 34869001, 2021). "In the oral cancer scRNA-seq study, the expression of TGFBI came from myCAFs, myofibroblasts and tumor cells." (PMID 34869001, 2021). "Taken together, the prognostic values of TGFBI and HYAL1 identified from betel quid-associated oral cancer tissues were recapitulated by seven (n=2834) and four (n=1048) TCGA cancer types, respectively." (PMID 34869001, 2021). "By incorporating disease-matched xenograft tissue and single-cell RNA-seq results, we suggested that TGFBI and HYAL1, primarily expressed by stromal CAFs and endothelial cells, respectively, could serve as robust prognostic biomarkers for oral cancer control." (PMID 34869001, 2021). "By translating the most significantly expressed gene matrix into clinical datasets of oral cancer tissues, we showed that the summed expression of FN1, TGFB2, TGFBR2, and TGFBI, dubbed the CAF index, is a poor indicator of overall survival for oral cancer (n=40) and the PANCAN (n=9,356) cohorts." (PMID 34869001, 2021).
oral lichen planus (1 paper, 2023). Oral lichen planus is a chronic inflammatory oral condition of unknown aetiology characterized by T-cell-mediated chronic immune response and abnormal epithelial keratinization cycle. "In a study of oral lichen planus (OLP) and normal skin tissues performing RNA-seq, molecules related to wound healing, KRT17, IL36G, TNC and TGFBI genes were significantly upregulated in OLP tissues." (PMID 37929023, 2023).
oropharyngeal carcinoma (1 paper, 2024). Carcinoma, predominantly squamous cell, arising from the epithelial cells of the oropharynx. "In a study of 94 patients with oropharyngeal carcinoma, high TGFBI expression in tumor stroma was an independent prognostic factor even after statistical adjustment for age, gender, smoking status, stage, grade and treatment." (PMID 38395907, 2024).
Photophobia (1 paper, 2009). Excessive sensitivity to light with the sensation of discomfort or pain in the eyes due to exposure to bright light. "Given the spectrum of phenotypic variability demonstrated in the TGFBI-associated dystrophies to date with the presence of photophobia and recurrent corneal erosions in many of the family members, mutational analysis of TGFBI was believed to be a valid first approach." (PMID 19710953, 2009).
Pigmentary retinopathy (1 paper, 2021). An abnormality of the retina characterized by pigment deposition. "Most of those causative genes, except TGFBI, were known to induce pigmentary retinopathy, which requires differential diagnosis from RP." (PMID 33946315, 2021).
polyp (1 paper, 2024). A usually exophytic mass attached to the underlying tissue by a broad base or a thin stalk. "Finally, through IF staining, we also revealed increased levels of TGFBI and LAMC2 in all three polyp subtypes." (PMID 38264936, 2024).
renal tumor (1 paper, 2024). "After verifying the knockdown of TGFBI expression, we performed CCK-8 to detect cell proliferation in renal tumor cells after knockdown of TGFBI." (PMID 39068456, 2024). "Taken together, these studies may suggest that TGFBI may be an EMT-associated inducer, which may be a new target for the treatment of renal tumor metastasis." (PMID 39068456, 2024). "To further understand the effect of TGFBI on the migration and invasion profiles of RCC cells, we assessed whether TGFBI affects the migration and invasion of renal tumor cells by wound healing assay and transwell assay." (PMID 39068456, 2024). "To further elucidate whether TGFBI can affect the biological behavior of renal tumor cells, we designed a series of experiments to evaluate it." (PMID 39068456, 2024). "However, the involvement of TGFBI in the process of renal tumor development and its mechanism has not been clarified for the time being." (PMID 39068456, 2024).
sarcoma (1 paper, 2021). A usually aggressive malignant neoplasm of the soft tissue or bone. "In most cancers, except CHOL, ESCA, sarcoma (SARC), SKCM and UCS, TGFBI expression was significantly correlated with immunoinhibitory genes." (PMID 34671645, 2021).
sarcopenia (1 paper, 2025). Progressive decline in muscle mass due to aging which results in decreased functional capacity of muscles. "Similarly, TGFBI-based interventions may benefit age-related sarcopenia, characterized by reduced regeneration and increased fibrosis." (PMID 41009607, 2025).
serous ovarian cystadenocarcinomas (1 paper, 2022). "“Gene module’ and ‘Diff Exp module’ within TIMER database were used to assess to analyze the correlative expression of TGFBI with different EMT modulators identified by proteomics on 303 serous ovarian cystadenocarcinomas." (PMID 36463238, 2022). "The statistical significance of the scatterplots between TGFBI expression and different genes of interest in a cohort of 303 serous ovarian cystadenocarcinomas was deduced using Spearman’s rho value." (PMID 36463238, 2022). "Amongst the proteomics identified and validated genes, the expression of TGFBI significantly positively correlated with the expression of GFPT2, FLNA, G6PD, ITGAV, ITGA1 and ITGA2 within the serous ovarian cystadenocarcinomas in TIMER database." (PMID 36463238, 2022).
skin cutaneous melanoma (1 paper, 2021). "The TGFBI mutation hotspot was R469C/H/S (missense mutation) in the FAS1 domain, which occurred in four cancers (UCEC, CESC, COAD, and skin cutaneous melanoma [SKCM]) in four patients." (PMID 34671645, 2021).
thymoma (1 paper, 2021). A neoplasm arising from the epithelial cells of the thymus. "TGFBI expression was negatively correlated with RNAss, and positively correlated with DNAss, in ACC, SARC, THCA, thymoma (THYM) and UVM." (PMID 34671645, 2021).
tongue squamous cell carcinoma (1 paper, 2022). A squamous cell carcinoma that arises from the tongue. "Similar as TGFBI, CXCR3 is also involved in the induction of epithelial-mesenchymal transition and thus in promoting metastasis and invasion of tongue squamous cell carcinoma." (PMID 36157879, 2022).
trauma (1 paper, 2012). "The increased deposits often appeared in the flap interface and mainly within the ablation zone, suggesting that an increased production of TGFBI protein by keratocytes in the region of corneal trauma was related to lamellar corneal incision and excimer laser ablation." (PMID 22355247, 2012).
tuberculosis (1 paper, 2020). A chronic, recurrent infection caused by the bacterium Mycobacterium tuberculosis. "Another marker, PSME4, has been associated with tuberculosis through in vitro and in vivo cultures, and is also related to CD4, IFNβ1, and TGFBI pathways." (PMID 33552042, 2020).
viral myocarditis (1 paper, 2022). Myocarditis that is caused by an infection with a viral agent. "We found that TGFBI and its coexpression genes enriched in several GOs and pathways like collagen fibril organization, PI3K-Akt pathway, and viral myocarditis." (PMID 36398072, 2022).
X-linked recessive disease (1 paper, 2024). X-linked recessive form of disease. "In detail, five autosomal dominant (AD) ophthalmic diseases caused by variants in ABCA4, CRYGD, MYOC, RPL1L1, and TGFBI, one AR disease caused by the PDE6B variant, and one X-linked recessive disease caused by the OCRL variant were determined as genetic causes." (PMID 38785568, 2024).
tumor (207 papers, 2002 to 2026). "The protein TGFBI (transforming growth factor-beta induced) is associated with tumor development, and its stability is regulated by the processes of ubiquitination and deubiquitination." (PMID 40430059, 2025). "Tumor-associated macrophages (TAMs) further divided into monocyte-derived brain macrophages (Mo-TAMs) expressed monocyte markers (TGFBI, VCAN, LYZ, and CLEC12A) and cells termed as Mg-TAMs expressed microglial signature genes (TMEM119, P2RY12, and P2RY13)." (PMID 39451239, 2024). "Intriguingly, TGFBI presented remarkably higher expression in tumor associated macrophages (TAMs) comparing to other cell types, which echoed the results we obtained above." (PMID 39068456, 2024). "Some researchers consider that TGFBI is a tumor suppressor because of the deficiency of TGFBI favors tumor formation, and high expression of TGFBI in tumor is associated with optimal chemotherapy sensitivity." (PMID 36906534, 2023). "Remarkably, M0‐like TAMs in tumor tissues overexpressed TGFBI and were associated with several well‐known tumor‐proliferation pathways." (PMID 35634956, 2022). "In another recent work, the authors demonstrated that TGFBI secreted by tumor-associated macrophages (TAM) promotes HGSOC‘s progression." (PMID 35053566, 2022). "Genome-wide DNA methylation profiling identified an EBV–AFB1 common signature within the TGFBI locus, which encodes for a putative tumor suppressor often altered in cancer." (PMID 35267594, 2022). "We found that tumor-associated macrophages (TAM) were the predominant cell type secreting TGFBI in STIC lesions." (PMID 34561272, 2021). "Tumor-associated macrophages promote OV cell migration, adhesion, and invasion by secreting TGFBI, and they have been associated with short PFS in high-grade serous OV patients." (PMID 34671645, 2021). "In conclusion, we investigated TGFBI expression characteristics, prognostic value, mutation profiles, associations with tumor-infiltrating immune cells, and associated molecular pathways in various types of cancer." (PMID 34671645, 2021). "Using patient serum samples and an orthotopic mouse model of CRC liver metastases we assessed the diagnostic/tumor targeting value of novel antibodies against TGFBI." (PMID 33408771, 2021). "Using TCGA data in cBioPortal (10,967 samples from 32 studies), we assessed the TGFBI alteration frequency and mutation count in tumor samples." (PMID 34671645, 2021). "Previously, TGFBI was considered to be a high-risk factor for increased incidence of spontaneous tumours in gastrointestinal tract cancers." (PMID 33614494, 2020). "Further analysis suggested that TGFBI expression was associated with gender, neoplasm histologic grade, and pathologic stage." (PMID 32406866, 2020). "Accordingly, tumour cells derived from TGFBI‐deficient mice have 37 times less tumour‐initiating capacity in limiting dilution assays." (PMID 33080107, 2020). "In this paper, we have linked the promoter DNA methylation-associated silencing of TGFBI with a possible tumor suppressor function in trastuzumab-resistant models." (PMID 31277676, 2019). "There are more causative evidences pointing to the controversial role of TGFBI in carcinogenesis, but multiple publications report a causative tumor promoting function of TGFBI42." (PMID 26857387, 2016). "We conducted human and animal studies to assess the role of TGFBI in tumorigenesis in an attempt to better understand the reasons underlying conflicting observations on the pro- and anti-tumor effects of TGFBI." (PMID 25889002, 2015). "We suspect that the basic mechanism underlying increased tumor incidence in Tg mice and sub-populations of TGFBI-overexpressing human cancer patients is that TGFBI promotes the survival of cells which have cancerous gene mutation." (PMID 25889002, 2015). "A significant association between TGFBI tissue expression with this progressive neoplasm at different stages and with its diameter was very recently reported." (PMID 26482227, 2015).